MADD (MAP kinase activating death domain)
Description:
Guanyl-nucleotide exchange factor that regulates small GTPases of the Rab family. Converts GDP-bound inactive form of RAB27A and RAB27B to the GTP-bound active forms. Converts GDP-bound inactive form of RAB3A, RAB3C and RAB3D to the GTP-bound active forms, GTPases involved in synaptic vesicle exocytosis and vesicle secretion (By similarity). Plays a role in synaptic vesicle formation and in vesicle trafficking at the neuromuscular junction (By similarity). Involved in up-regulating a post-docking step of synaptic exocytosis in central synapses (By similarity). Probably by binding to the motor proteins KIF1B and KIF1A, mediates motor-dependent transport of GTP-RAB3A-positive vesicles to the presynaptic nerve terminals (By similarity). Plays a role in TNFA-mediated activation of the MAPK pathway, including ERK1/2. May link TNFRSF1A with MAP kinase activation. May be involved in the regulation of TNFA-induced apoptosis.
Synonyms: RabGEF; Rab3GEP; DENN; IG20; KIAA0358; DEEAH; NEDDISH
Tractability: Antibody: UniProt places it where antibodies can reach, with high confidence; its Gene Ontology location is reachable by antibodies, with high confidence. PROTAC: ubiquitination databases record sites on it; its protein half-life has been measured.
Gene: Protein-coding gene on chromosome 11 (47,269,161 to 47,330,038, forward strand). Ensembl gene ENSG00000110514.
Subcellular location: Cell membrane; Cytoplasm; Cell projection, axon
Subcellular location (Human Protein Atlas): Cytosol; Plasma membrane
Pathways (Reactome):
Signal Transduction: Regulation of TNFR1 signaling
Vesicle-mediated transport: RAB GEFs exchange GTP for GDP on RABs
Gene Ontology:
Molecular function: guanyl-nucleotide exchange factor activity; protein binding; death receptor binding; protein kinase activator activity
Biological process: execution phase of apoptosis; positive regulation of MAPK cascade; regulation of apoptotic process; regulation of cell cycle; regulation of extrinsic apoptotic signaling pathway; regulation of extrinsic apoptotic signaling pathway via death domain receptors; regulation of Rab protein signal transduction; cell surface receptor signaling pathway
Cellular component: cytosol; membrane; plasma membrane; cytoplasm; axon
Genetic constraint (gnomAD): Loss-of-function variants: 104 observed, 168.9 expected, observed/expected ratio (o/e) 0.62, 90% interval 0.52 to 0.73. The upper end of that interval is the gene's LOEUF score, 0.73, which puts it in group 2 of 6, group 1 being the genes least tolerant of losing a copy. Missense variants: 1,830 observed, 2,062.1 expected, observed/expected ratio (o/e) 0.89, 90% interval 0.85 to 0.92. Synonymous variants: 744 observed, 785.17 expected, observed/expected ratio (o/e) 0.95, 90% interval 0.89 to 1.01.
Homologues: Orthologues: chimpanzee MADD (99% identical), dog MADD (97% identical), macaque MADD (96% identical), rabbit MADD (96% identical), pig MADD (96% identical), rat Madd (95% identical), mouse Madd (94% identical), guinea pig MADD (93% identical), tropical clawed frog madd (78% identical), zebrafish madd (75% identical), Drosophila melanogaster Rab3-GEF (43% identical), Caenorhabditis elegans aex-3 (34% identical).
Diseases named in the same sentence as MADD in open-access papers:
MADD is named in the same sentence as 64 diseases in open-access papers, as found by Europe PMC text mining. Sharing a sentence is not in itself a finding about the gene and the disease. The quoted sentences say what the papers report.
Alzheimer disease (7 papers, 2017 to 2025). A progressive, neurodegenerative disease characterized by loss of function and death of nerve cells in several areas of the brain leading to loss of cognitive function such as memory and language. "The TNFR1 and MADD interact with each other and mediate downstream protein signaling pathways which cause neuronal cell death and Alzheimer’s disease." (PMID 34112868, 2021). "In Alzheimer's disease, a reduction in DENN/MADD levels is shown to be associated with neuronal death." (PMID 40812422, 2025). "The death domains of TNFR1 and MADD could be used as a novel pharmacological target for the treatment of Alzheimer’s disease by inhibiting the MAPK pathway." (PMID 34112868, 2021). "The proposed mechanistic pathways ensure the significance of TNFR1 and MADD interactions that could be used as a novel target for development of drugs for the treatment of Alzheimer’s disease." (PMID 34112868, 2021). "In Alzheimer’s disease brains, APP-overexpressing mice, and neuronal cells exposed to Aβ, there is a reduction in MADD expression at both the protein and mRNA levels, accompanied by alterations in MADD splicing, which can further promote neuronal cell death." (PMID 40659647, 2025). "A research on neuronal cell death in Alzheimer's disease has shown significant down-regulation of DENN/MADD and enhanced hippocampal neuronal death following DENN/MADD silencing." (PMID 28323882, 2017). "Thus, downregulation of MADD, a TNF receptor‐binding protein, correlates with neuronal death in Alzheimer's disease." (PMID 35049090, 2022). "Additionally, DENN/MADD, a multifunctional domain protein, interacts with JNK, activating MAPK/JNK pathway in Alzheimer’s disease (AD) pathogenesis." (PMID 34395234, 2021).
type 2 diabetes (5 papers, 2010 to 2025). "DENN/MADD is known to mediate glucose-induced insulin secretion in pancreatic β-cells; disruption of this pathway can cause type II diabetes." (PMID 40812422, 2025). "The A allele at SNP rs7944584 and the G allele at SNP rs10501320 in MADD locus have been associated with higher fasting blood glucose levels and rs7944584-A and 8 additional nonsynonymous MADD variants with type 2 diabetes." (PMID 38775154, 2024). "Most of these associations were in consistence with findings in the European descent samples, except that MADD rs7944584 showed an association to type 2 diabetes only in the Chinese samples." (PMID 21103350, 2010). "More recently, another study in a case-control sample of Chinese also replicated the associations of DGKB, MADD, GLIS3, PROX1 and IGF1 with type 2 diabetes and/or glycemic traits." (PMID 21747906, 2011). "Additionally, the associations of MADD, ADRA2A, IRS1 and FASD1 with type 2 diabetes or its related traits were directional different between two subpopulations." (PMID 21747906, 2011). "Although the associations between the SNPs in MADD, ADRA2A, C2CD4B, IGF1, IRS1and FADS1 with fasting glucose or type 2 diabetes were directionally consistent with those observed for white Europeans and of similar magnitude to that observed in the previous GWAS, none reached nominal significance." (PMID 21747906, 2011). "We showed SNPs from seven loci, including GIPR, TCF7L2, MADD, CRY2, GLIS3, PROX1 and SLC30A8, had an effect on type 2 diabetes in our samples." (PMID 21103350, 2010). "SNPs in or near MADD, ADRA2A, PROX1, FADS1, C2CD4B, IGF1, and IRS1 did not exhibit significant associations with type 2 diabetes or related glycemic traits (P≥0.10)." (PMID 21747906, 2011).
leukemia (4 papers, 2010 to 2025). A malignant (clonal) hematologic disorder, involving hematopoietic stem cells and characterized by the presence of primitive or atypical myeloid or lymphoid cells in the bone marrow and the blood. "Later studies reported the involvement of DENN/MADD in promoting cancer cell survival in the context of leukemia, neuroblastoma, thyroid and lung cancer." (PMID 28323882, 2017). "Thus, future experiments should include a time course and testing on primary leukemia with cell surface markers to resolve the cellular mechanisms and subpopulations driving the MADD signaling profile." (PMID 40745386, 2025). "In the past, we showed that ART induced apoptosis in KG-1a leukemia cells, and that a number of apoptosis-regulating genes (LOC51272, CIDEB, PDCD2, BAG1, BAG3, MADD) correlated with cellular responses towards ART." (PMID 20428086, 2010).
diabetes (3 papers, 2012 to 2021). "Novel variants in the genes ARAP1, GLIS3, MADD, NOTCH2 and WFS1 need further investigation to reveal their possible role in diabetes." (PMID 22662265, 2012).
non-small cell lung carcinoma (3 papers, 2016 to 2022). A group of at least three distinct histological types of lung cancer, including non-small cell squamous cell carcinoma, adenocarcinoma, and large cell carcinoma. "For example, miR-1197 controls the progression of non-small-cell lung carcinoma through regulating MADD, and also promotes cell proliferation by upregulating HOXC11." (PMID 34986861, 2022).
breast carcinoma (2 papers, 2013 to 2023). "MADD expression was determined by immunofluorescence staining using an exon 13L-specific antibody in three breast cancer cell lines (i.e. MCF-7, MDA-MB-231 and T47D cells)." (PMID 23457619, 2013). "Collectively, these results indicated that activation of the extrinsic pathway was critical not only for enhanced TRAIL-induced apoptosis but also for doxorubicin-induced apoptosis in breast cancer cells with MADD knock down." (PMID 23457619, 2013). "We have previously shown enhanced levels of expression of MADD in multiple cancer tissues including a limited number of breast cancer tissues." (PMID 23457619, 2013). "To determine if MADD is expressed differentially we stained breast cancer tissue microarrays using a MADD reactive antibody." (PMID 23457619, 2013). "In summary, our results show that in addition to the enhancement of TRAIL-induced apoptosis, MADD knockdown could synergize the apoptotic effects of doxorubicin in breast cancer cells." (PMID 23457619, 2013). "MADD knockdown resulted in enhanced spontaneous apoptosis in human breast cancer cell lines." (PMID 23457619, 2013). "Therefore, we investigated the combined effects of MADD knock down in breast cancer cells with doxorubicin treatment." (PMID 23457619, 2013). "Hence, we examined whether MADD knockdown could enhance TRAIL induced apoptosis in breast cancer cells." (PMID 23457619, 2013). "Therefore, we speculated that MADD might be over-expressed in human breast cancer tissues and that MADD knock-down might synergize with chemotherapeutic or TRAIL-induced apoptosis of breast cancer cells." (PMID 23457619, 2013). "Oncogenic splicing switches driven by hnRNP H include targets such as IG20/MADD in glioma, TCF3 in lymphoma, HER2 and Mcl-1 in breast cancer, KHK in hepatocellular carcinoma, and A-Raf in colon and head and neck cancers." (PMID 37399401, 2023). "Here, we have demonstrated that the pro-survival protein MADD, an isoform of the IG20 gene, is significantly over expressed in breast tissues containing DCIS and invasive breast cancer, as well as in the three evaluated breast cancer cell lines." (PMID 23457619, 2013). "Therefore, we examined MADD expression in breast cancer tissues and tested the effects of MADD knockdown on TRAIL and doxorubicin induced apoptosis of breast cancer cells." (PMID 23457619, 2013). "However, neither the levels of expression of MADD in breast cancer tissues nor its ability to confer resistance to chemotherapeutic or TRAIL induced apoptosis in breast cancer cells has been investigated." (PMID 23457619, 2013).
glioblastoma (2 papers, 2023). The most malignant astrocytic tumor (WHO grade IV). "For example, the expression of the isoforms CXCL12 and IG20/MADD changes during the progression of glioblastoma." (PMID 36675796, 2023). "hnRNP H drives an oncogenic switch in glioblastoma multiforme (GBM) cells by promoting of aberrant splicing of MADD and RON, whereas H1/H2-mediated unsplicing of thymidine phosphorylase results in antitumor drug resistance in leukemia cells." (PMID 36830718, 2023).
glioma (2 papers, 2014 to 2023). A benign or malignant brain and spinal cord tumor that arises from glial cells (astrocytes, oligodendrocytes, ependymal cells). "For instance, upregulation of hnRNP H in gliomas drives the IG20 to anti-apoptotic MADD (MAP-kinase activating death domain protein) splicing in favor of invasiveness." (PMID 25523808, 2014).
Hyperglycemia (2 papers, 2020 to 2024). An increased concentration of glucose in the blood. "Therefore, we recommend that the patients with deleterious MADD variants are followed up until early adulthood for the presence of hyperglycemia and diabetes." (PMID 38775154, 2024).
insomnia (2 papers, 2022 to 2023). A sleep disorder characterized by difficulty in falling asleep and/or remaining asleep. "Moreover, an integrative analysis based on an insomnia GWAS dataset and brain region-related enhancer maps indicated that the MADD gene was significantly associated with insomnia, revealing its role in insomnia and other mental disorders." (PMID 35893077, 2022).
insulinoma (2 papers, 2015 to 2025). "MADD, a splice variant of IG20 (insulinoma-glucagonoma 20) overexpressed in cancer cells, is crucial for RAS/MEK/ERK activation by facilitating recruitment of Grb2 to the receptor-mediated signaling complex." (PMID 26517243, 2015).
intrahepatic cholangiocarcinoma (2 papers, 2025). A carcinoma that arises from the intrahepatic bile duct epithelium in any site of the intrahepatic biliary tree. "Glycolysis promotes P300-catalyzed nucleolin lactylation, which triggers ERK signaling and upregulates MAP kinase-activating death domain protein (MADD) expression through accurate mRNA splicing to cause intrahepatic cholangiocarcinoma (iCCA) formation." (PMID 40295451, 2025). "Meanwhile, MADD expression levels can be assessed using qPCR or ELISA, and its specific splice variants are expected to serve as prognostic indicators for intrahepatic cholangiocarcinoma, aiding in evaluating tumor malignancy and metastatic potential." (PMID 41458606, 2025).
melanoma (2 papers, 2016). A malignant, usually aggressive tumor composed of atypical, neoplastic melanocytes. "Interestingly, the PSI of the MADD isoform that skips exon 16 is higher in the group with worse prognosis, suggesting that the anti-apoptotic function of MADD is related to worse prognosis in invasive melanoma." (PMID 27535130, 2016).
muscular dystrophy (2 papers, 2024 to 2025). Muscular dystrophy (MD) refers to a group of more than 30 genetic diseases characterized by progressive weakness and degeneration of the skeletal muscles that control movement. "Monoallelic DENN/MADD variants have been linked to autism and muscular dystrophy, whereas biallelic variants in DENN/MADD result in a neurological disorder or a multisystem disorder." (PMID 40812422, 2025). "Although heterozygous missense variants in MADD have been also associated with muscular dystrophy, but the heterozygous parents (of our Patients 3 and 4 who had missense variant) were unaffected." (PMID 38459224, 2024).
arthrogryposis (1 paper, 2024). A rare, non-progressive congenital disorder characterized by multiple joint contractures which are present at birth. "Future studies will decipher the precise mechanisms through which MADD deficiency leads to arthrogryposis, genital anomalies and structural brain anomalies." (PMID 38459224, 2024). "We describe the clinical manifestations observed in 5 patients with homozygous novel likely disease-causing variants in the MADD gene that presented with neurodevelopmental delay as well as arthrogryposis." (PMID 38459224, 2024). "Additionally, our results suggest that patients with MADD variants are likely to have variable degrees of arthrogryposis, structural brain, congenital heart disease, and genital anomalies." (PMID 38459224, 2024).
bronchogenic carcinoma (1 paper, 2024). A lung carcinoma arising from the bronchial epithelium. "Tipgomut and colleagues also exhibited that melittin inhibited cellular proliferation and apoptosis induction through the Bcl-2 upregulation and MADD downregulation in Chago-K1 human bronchogenic carcinoma cells." (PMID 38445441, 2024).
cardiac hypertrophy (1 paper, 2020). "Since MAP kinase plays an important role of cardiac hypertrophy, the association between rs1052373 polymorphism and VO2max and endurance may also be explained by MADD expression, although this needs further validatoin." (PMID 32612638, 2020).
cholangiocarcinoma (1 paper, 2025). A carcinoma that arises from the intrahepatic biliary tree (intrahepatic cholangiocarcinoma) or from the junction, or adjacent to the junction, of the right and left hepatic ducts (hilar cholangiocarcinoma). "In cholangiocarcinoma, lactylation at the K477 site of nucleolin (NCL) enhances MADD protein translation activity by modulating MADD RNA splicing." (PMID 40589733, 2025).
deeah syndrome (1 paper, 2024). "Human KMT2C, MADD and TCF4 are causative genes for three neurodevelopmental disorders, Kleefstra syndrome 2, DEEAH syndrome and Pitt-Hopkins syndrome, respectively." (PMID 37294900, 2024).
diastolic heart failure (1 paper, 2012). Heart failure caused by abnormal myocardial relaxation during diastole leading to defective cardiac filling. "Association between MYBPC3 and MADD gene sequence variants and Diastolic Heart Failure." (PMID 22529996, 2012).
epilepsy (1 paper, 2025). A brain disorder characterized by episodes of abnormally increased neuronal discharge resulting in transient episodes of sensory or motor neurological dysfunction, or psychic dysfunction. "MADD positively regulates a downstream step of synaptic exocytosis, and mutations in this gene have been included in the early-onset or syndromic epilepsy v4.164 panel." (PMID 40076950, 2025).
Failure to thrive (1 paper, 2024). Failure to thrive (FTT) refers to a child whose physical growth is substantially below the norm. "Biallelic pathogenic variants in MADD lead to a very rare neurodevelopmental disorder which is phenotypically pleiotropic grossly ranging from severe neonatal hypotonia, failure to thrive, multiple organ dysfunction, and early lethality to a similar but milder phenotype with better survival." (PMID 38459224, 2024).
Glucose intolerance (1 paper, 2023). Glucose intolerance (GI) can be defined as dysglycemia that comprises both prediabetes and diabetes. "MADD gene, also known as IG20, plays a critical role in the development of glucose intolerance and AD." (PMID 37342358, 2023).
Hypotonia (1 paper, 2024). Hypotonia is an abnormally low muscle tone (the amount of tension or resistance to movement in a muscle). "Hypotonia is a cardinal feature of MADD gene dysfunction being reported previously in 100% of cases in the lethal group." (PMID 38459224, 2024).
multiple sclerosis (1 paper, 2017). A progressive autoimmune disorder affecting the central nervous system resulting in demyelination. "We have also observed decreased DENN/MADD expression levels in the nervous system of EAE mice, an experimental animal model of multiple sclerosis." (PMID 28323882, 2017).
ovarian carcinoma (1 paper, 2022). A malignant neoplasm originating from the surface ovarian epithelium. "Studies examining the role of the IG20 gene in ovarian cancer revealed that MADD is necessary for malignant cell survival compared to the other three splice variants in PA-1 ovarian carcinoma cells." (PMID 36551731, 2022). "Many studies have focused on the necessity of MADD in apoptosis because the loss of MADD expression has been shown to increase cellular proliferation and metastasis in thyroid, cervical, breast, lung, and ovarian cancer." (PMID 36551731, 2022). "While MADD has not been extensively studied in drug-resistant ovarian cancer, it is known to be a splice variant of the insulinoma-glucagonoma clone 20 (IG20) gene, which has been studied." (PMID 36551731, 2022).
pancreatic exocrine insufficiency (1 paper, 2025). "Biallelic DENN/MADD variants have pancreatic exocrine insufficiency, leading to a deficiency of exocrine pancreatic enzymes disrupting digestion." (PMID 40812422, 2025).
retinoblastoma (1 paper, 2024). A malignant tumor that originates in the nuclear layer of the retina. "Group 3 MB and retinoblastoma, along with the normal cerebellum and retina —both of which are known to express high levels of OTX2—exhibited unique PPHLN1 and MADD splicing patterns." (PMID 39025928, 2024).